SOX9 (SRY-box transcription factor 9)
Diseases named in the same sentence as SOX9 in open-access papers (continued):
Sharing a sentence is not in itself a finding about the gene and the disease.
tumor (continued). "Semi-quantitative scoring indicated that both SOX9 and COL10A1 protein levels were significantly higher in tumor tissues." (PMID 30154451, 2018). "Remarkably, amongst the top hits we recovered SOX9, a key stem factor reported to be co-expressed in SOX2+ tumor-initiating SCCs37,38." (PMID 30467425, 2018). "We found that SOX9 is upregulated in SWCNT-exposed cells, which is consistent with their abilities to induce tumor formation and metastasis in vivo." (PMID 28912540, 2017). "Biomarker expression of CXCR4, SMAD4, SOX9 and IFIT3 will be prospectively assessed by immunohistochemistry and verified by rt.-PCR from tumor and adjacent healthy pancreatic tissue of surgical specimen." (PMID 28356064, 2017). "In this study, we assessed and compared the immunohistochemical expression of stemness markers EpCAM, Sox9 and CK19 in HCC tissues from a cohort of liver explant cases consisting of multiple tumor nodules." (PMID 28764740, 2017). "These samples are used to confirm immunohistochemistry analysis using reverse transcription quantitative polymerase chain reaction (RT-qPCR) as a second method to analyze CXCR4, SMAD4, SOX9 and IFIT3 mRNA expression of the tumor." (PMID 28356064, 2017). "HCCs with microscopic vascular invasion had high mRNA levels of HAPLN1, LGR5, LEF1, SOX9, CD44, Glypican 3 and larger tumor size." (PMID 27191501, 2016). "We further showed by RT-qPCR and immunofluorescence that SOX9 and OPN are expressed equally in all tumor types." (PMID 27280413, 2016). "As expected, we observed a significant decrease of tumor development from grafted and doxycycline induced S9-CT26 cells, indicating that SOX9 is also able to impair the metastasis potential of CRC cells." (PMID 27429045, 2016). "When investigating the SKCM dataset, we found SOX9, SOX2 as well as SOX6 to be down-regulated in the tumor subgroup of low SOX5 expression compared to the tumor subgroup of high SOX5 expression." (PMID 26927636, 2016). "After adjustment, tumor size, tumor differentiation, AJCC stage, SOX9 expression, and S100P expression were identified as covariates." (PMID 26009899, 2015). "Scenario 3 included SOX9 expression, preoperative PSA, clinical tumor stage (cT stage) and Gleason grade obtained on the prostatectomy specimen." (PMID 26030748, 2015). "An increased expression of SOX9 and SOX2 protein has also been described for EA tumor cell lines compared to BE cells." (PMID 24714516, 2014). "Interestingly, Aurora kinase A is dramatically overexpressed in MPNST cell lines and its inhibition may limit tumor cell growth; additionally, in vitro targeting of SOX9 (Sex-determining-region Y-box 9) by shRNA (short hairpin RNA) reduces MPNST cell survival and increases death." (PMID 24303016, 2013). "We noticed that VEGFA, HIF1A, SOX4, SOX9, MMP2, TGFB1 genes are overexpressed together with S6K1 in all 4 tumour types investigated." (PMID 22570651, 2012). "The aim of this study was to investigate the expression of SOX9 in HCC and determine its correlation with tumor progression and prognosis." (PMID 22515642, 2012). "The subsequent analysis in primary MCL identified five genes (SOX9, HOXA9, AHR, NR2F2, and ROBO1) frequently methylated in these tumours." (PMID 21603610, 2011). "Tumor tissues from the sh‐SOX9+vector group displayed a significant reduction in Ki67‐positive cells and an increase in TUNEL‐positive cells, whereas the sh‐SOX9+TIMP1 group showed the opposite pattern." (PMID 41270217, 2026). "In contrast to SOX2, SOX9 show not cell specificity, as it expression expanded from hair follicles in normal skin to the basal layer in tumours across all models, regardless of cell of origin." (PMID 41507151, 2026). "In parallel, PTEN loss increases SMAD4 expression and sensitizes the tumor cells to TGFβ signaling, with TGFβ treatment repressing SOX9 expression in tumor cells lacking PTEN." (PMID 41646383, 2026).
tumor (continued). "Both tumor weight and volume were significantly reduced in the NPs@si‐SOX9/CL and iRGD NPs@si‐SOX9/CL groups compared with PBS, with more pronounced suppression observed in the NPs@si‐SOX9/CL+L and iRGD NPs@si‐SOX9/CL+L groups." (PMID 41270217, 2026). "Therefore, given the inhibitory effect of AS‐F‐NP on methionine uptake by tumor cells, we further examined the changes in H3K4me3 and the CSC marker SOX‐9 and ALDH1 in 4T1 cells after AS‐F‐NP treatment." (PMID 39985256, 2025). "The data suggest Sox9 inactivation promotes tumor progression rather than simply exacerbating phenotypes instigated by Apc inactivation." (PMID 40179020, 2025). "DHCR24 is a direct target of the stem cell regulator SOX9, and in a diffuse large B‐cell lymphoma (DLBCL) cell line xenograft model, knockdown of SOX9 resulted in reduced DHCR24 levels, decreased cholesterol content, and reduced tumor load." (PMID 40145543, 2025). "While most tumor meta-programs exhibited melanocytic differentiation (high MITF and CTNNB1), two meta-programs-Respiration and Stress-expressed dedifferentiation markers including AXL, SOX9, EGFR and NGFR." (PMID 40890106, 2025). "Interestingly, the spatial clusters C3 and C5 both expressed high levels of stem cell markers OLFM4, SOX9, and ANPEP, corresponding to the metaplasia and tumor regions, respectively." (PMID 39950944, 2025). "The Sex-determining Region Y-related High-Mobility Group Box 9 (SOX9), a key transcription factor in the SOX family, plays essential roles in various biological processes, particularly in the development of the tumor microenvironment and the repair of inflamed tissues." (PMID 41293317, 2025). "Second, while we have identified two CSC markers including SOX9 and OLFM4 at single‐cell resolution and in vitro experiments, in vivo functional validation in animal models to confirm the role of CSCs in tumor initiation, progression, and resistance is still required." (PMID 39950944, 2025). "On the other hand, we found 21% of the tumor samples studied showed absent or negligible SOX9 staining." (PMID 40179020, 2025). "Remarkably, in Sox9-deleted livers, clonal growth of hepatocytic cells was apparent for all three oncogenes, with especially extensive proliferation in the AKT* group, where visible tumours were observed." (PMID 41290681, 2025). "Interestingly, the cancer stem cell marker SOX9 gene expression level was also increased in the PDX cell line compared with the donor BC tumor." (PMID 40801146, 2025). "CMD‐BHQ3‐PTL/DOX@RBCm efficiently inhibited CRC cells in vitro and demonstrated remarkable anti‐tumor effects in vivo, providing novel insights for nanomedicine optimization and deepening our understanding of the role of the Hippo/YAP1/SOX9 pathway in CRC development." (PMID 39523731, 2025). "However, aberrant SOX9 expression has been detected in the majority of PDAC cases with poor prognosis and it has been shown that SOX9 expression promotes PDAC tumor formation." (PMID 40619489, 2025). "The original tumors were positive for AFP and HepPar1 similarly to transplanted HepYF-M13 tumors but showed reduced Sox9 and no significant Krt19 expression in tumor cells." (PMID 39051113, 2024). "Here, we revealed that liver-specific developmental Sox9 elimination using Alb-Cre;Sox9(flox/flox) (LKO) and CRISPR/Cas9-based tumor-specific acute Sox9 elimination (CKO) in SB-HDTVI-based Akt-YAP1 (AY) and Akt-NRAS (AN) cHCC-CCA models showed contrasting responses." (PMID 39273023, 2024). "With integrative analysis of whole genome CRISPR screening data from DepMap Project, GBC RNAseq data, and the Coltron prediction results, five CRC TFs (SOX9, TCF7L2, FOXA1, TGIF1 and HES1) were found to meet all our defined criteria for gene expression and tumor‐dependency levels." (PMID 39492805, 2024).
tumor (continued). "IHC staining of these xenograft tumours for previous stem cell-like markers, compared to the control xenograft tumours, showed that the percentage of CD44, NANOG, SOX9, SOX2 positive cells was reduced in the STC1-silenced group, and STC1 shRNA and circUBA2 co-transfection played a reversal role." (PMID 39103836, 2024). "However, when cells lose the expression of MEG8, SOX9 activity and its downstream target BMI1, proliferation is promoted, bypassing senescence and facilitating tumor formation and progression." (PMID 39706842, 2024). "As SOX9 is involved in the pathogenesis and progression of OSCC and the crosstalks between tumor cells and stromal cells, this factor could be one of the stimuli underlying the VGF upregulation in OSCC." (PMID 38528565, 2024). "However, we previously reported that SOX9 is dispensable in NOTCH-driven HC-to-BEC/iCCA reprogramming, whereas it is involved in tumor cell viability and proliferation in Akt-NICD HC-derived iCCA models." (PMID 39273023, 2024). "Notably, Akt-YAP1 in Sox9 LKO led to significantly decreased survival and a much greater and more lethal tumor burden, as seen by significantly greater LW/BW and macroscopically, as compared to the Akt-YAP1 in LWT mice." (PMID 39273023, 2024). "SOX2 silencing significantly increased the number of tumor spheres with a significant reduction in colony size when compared to SOX9 silencing and control cell lines, whereas SOX9 silencing did not affect the tumor sphere formation or size of the colonies." (PMID 38275880, 2024). "Herein, we reveal that unlike chronic developmental Sox9 deletion, the acute and therapeutic elimination of Sox9 reduces overall cHCC-CCA tumor burden in Akt-YAP1 but not the Akt-NRAS model." (PMID 39273023, 2024). "Finally, CA3 suppressed EAC tumor growth in a mouse xenograft model, whereby tumor cell growth suppression was attributed to the inhibition of YAP and SOX9, which are important for CSC maintenance." (PMID 37628858, 2023). "Live tumor cells treated with anti-KRAS antibody also showed less intense cytoplasmic and less nuclear staining for SOX9, thus providing further evidence that SOX9, a cancer stem cell marker and potential driver in CRC, is a downstream effector of KRAS signaling." (PMID 37051535, 2023). "Moreover, we discovered that JMJD1C, a chromatin factor, is a novel binding partner of SOX9, and depletion of JMJD1C impairs OS tumor growth." (PMID 37491298, 2023). "Instead, tumor-like ductular proliferations were positive for CK19 and SOX9 staining." (PMID 37174657, 2023). "In addition, the SOX9/CXCL5 axis also facilitates the infiltration of macrophages and neutrophils in tumor tissue." (PMID 37907984, 2023). "Importantly, tumoral c-Jun expression was positively correlated with SOX9, SOX2, OCT4, FTH1, FTL and TFRC expression in consecutive PDAC tumour tissues." (PMID 37143164, 2023). "Compared to untreated cells or tumor cells treated with rabbit IgG negative control, tumor cells treated with anti-KRAS antibody showed weaker SOX9 cytoplasmic staining and less nuclear localization." (PMID 37051535, 2023). "Also, the progenitor/stemness markers SOX9, CD44v6, CD133, and EPCAM were highest in the tumor lesions." (PMID 35655220, 2022). "The protein levels of tumor SOX9 are not significantly different between Duke’s stage A/B and C/D or between right‐ and left‐sided colon." (PMID 34919787, 2022). "And now based on gene expression patterns, it further indicated that lymph node metastatic tumor cells are more likely originated from OLFM4+SOX9+ C-type cells (PT-b), but not from OLFM4+SOX9- C-type cells (PT-a) in the primary tumor." (PMID 35974387, 2022). "We hypothesize that the inhibition of SOX9 and SOX18 expression by complex C1 can be used to further sensitize the tumor for the conventional therapy." (PMID 35408514, 2022).
tumor (continued). "In conclusion, our study reveals that OTUD1 potentially acts as a tumor suppressor and suppresses erlotinib resistance of NSCLC through the YAP1/SOX9/SPP1 axis, suggesting that OTUD1 may serve as a target for reducing chemoresistance for NSCLC." (PMID 36182943, 2022). "Conversely, Sox9 (a Wnt and Yap1-target gene) and some canonical targets of Yap/Tead such as Cyr61 and IL33 which have known roles in stem cell maintenance, cell migration and tumor invasiveness - were repressed by AHR." (PMID 35383166, 2022). "We further utilize bulk RNA-seq data and found a significant upregulation of SOX9, IL32, and SLC22A6 (PT2), and downregulation of SLC22A6/ SLC22A8 (PT1) in tumor compared to adjacent normal tissue, confirming our cell origin hypothesis on PT2 cells." (PMID 36180422, 2022). "Notably, our NI‐WB results indicated that SOX9 protein is upregulated in the tumor compared to matched mucosa, and KRAS G12D or pooled KRAS mutant had significantly higher SOX9 protein levels than WT tumors." (PMID 34919787, 2022). "In the primary tumor, we observed only a small population (4%) that co-expressed NR2F1 and SOX9." (PMID 35110548, 2022). "Compared with A375 cells, A375 xenograft tumor displayed an upregulation for glial and neuronal genes (GFAP, BDNF, MAP2, MTURN, ROBO2, SYT1 and TUBB3) and neural stemness genes (ASCL1, MSI1, PAX6, PDGFRA, SOX9, VIM, ZIC1/2)." (PMID 33468253, 2021). "Our results confirmed the high expression of SOX9 in tumor tissues compared to the adjacent non-tumor tissues." (PMID 34124145, 2021). "Liver injury, induced by hepatotoxin 3,5-diethoxycarbonyl-1,4-dihydrocollidine (DDC) or high-fat diet (HFD), substantially increases tumor incidence and accelerates liver carcinogenesis from SOX9+ cells in Pten null mice but not in control mice." (PMID 34083580, 2021). "Based on the scoring method, none of the tumor sections revealed strong and intensive expression of SOX9 in tumors." (PMID 33736633, 2021). "Expression of CK19, SOX9, LGR5, and LRIG1 in MCC and normal human skin was studied by immunohistochemistry, and the staining patterns or intensities were statistically correlated with patient, tumor, MCPyV, and survival parameters." (PMID 34331569, 2021). "Furthermore, a previous report concluded that SOX9 also inhibited CDX2 protein expression both in intestinal adenocarcinoma cells in vitro and in a nude mouse xenograft tumor model." (PMID 33639844, 2021). "However, our data minimally demonstrate that SHP-2 intrinsically regulates SOX-9 expression in YFP marked cells, reinforcing the critical tumor suppressor role of SHP-2 in a subset of chondrocyte-like cells." (PMID 34625577, 2021). "Analysis of cells treated with AZD4573 showed that the levels of Sox2 and Sox9 are reduced, implying that inhibiting CDK9 might prevent their tumor promoting functions." (PMID 34359807, 2021). "All tumor cells express YFP, indicating that they originate from the SOX9+ cells." (PMID 34083580, 2021). "Notably, the correlation of SOX9 with cellular signaling pathway likewise NOTCH and Wnt, spotted this transcription factor as an appealing effector tumor cell fate." (PMID 33736633, 2021). "IHC revealed expression of Sox1, Sox9, Map2, Acta2, Bglap and Afp in sections, indicating the presence various types of neural and non-neural tissues or cells in tumor." (PMID 33468253, 2021). "Indeed, our results show that this axis promotes tumor cell survival and proliferation via p21CIP, since the restoration of BMI1 levels in SOX9 silenced cells, also modulated, in this case inhibited, the expression of this tumor suppressor." (PMID 31941916, 2020). "Indeed, Sox9 expression, together with the cytokeratin profile of human BCC, would suggest a differentiation of these tumours along the ORS." (PMID 32397255, 2020). "Results manifested that the absence of SOX9 hindered the formation of secondary and tertiary tumor spheres from CRC cells." (PMID 33318478, 2020).
tumor (continued). "For instance, high levels of expression of SOX9, which is regulated by DNA methylation, was found to be correlated with decreased expression of tumor suppressor genes and was identified to be a negative prognostic factor in malignant SKCM." (PMID 32902917, 2020). "Indeed, both SOX9 and RUNX2 can act as oncogenes or tumor suppressors in a context-dependent manner—their expression is characteristic for cancer stem-like cells (CSCs) and they are involved in metastasis and chemoresistance." (PMID 33287223, 2020). "Sox9 mRNA expression was demonstrated in all tumour types analyzed, except for PM that showed very low/absent levels of expression when compared with values obtained from normal skin samples." (PMID 32397255, 2020). "Specific HCC tumor markers, such as CK19, Sox9, and EpCAM, were expressed in all analyzed passages." (PMID 31726709, 2019). "Studies on samples from pediatric patients with SPT showed that PDX1 and SOX9 were both expressed in the cytoplasm of SPT cells, supporting the hypothesis that tumor cells originate from pancreatic stem cells persisting after the embryonic period." (PMID 31057614, 2019). "In expansive tumours, the 5-year disease-free survival of patients with SOX9-positive tumours was 87% versus 57% of patients with SOX9-negative tumours (P = 0.01)." (PMID 31275454, 2019). "ELDA (extreme limiting dilution analysis) assay demonstrated that lack of Sox9 significantly reduced the frequency of tumour-initiating cells by 4.76-fold (p = 0.00427) in tamoxifen-resistant cells." (PMID 30622340, 2019). "Clinically, high expression of SOX9 in cytoplasm could be related with a poor disease-free survival (DFS), overall survival, higher tumor grade, and worse disease-specific survival compared to patients with nuclear SOX9." (PMID 31057614, 2019). "As described, epigenetic modification of tRNA (U34) further supports tumorigenesis by up-regulating U34 enzymes and enhancing codon wobble of especially tumor promoting genes, an effect that prominently involves SRY-box 9 (SOX9) and elongator complex protein 3 (Elp3)." (PMID 30921315, 2019). "In contrast, all tumors strongly express EGFR and the hair follicle stem cell marker SOX9 at the highly proliferative tumor-stroma interface, whereas central tumor regions with a more differentiated stratum spinosum cell type lack both EGFR and SOX9 expression." (PMID 31867038, 2019). "The result showed that the tumor treated by TMZ combined with SOX9 shRNA or PDK1 inhibitor grew much slower that TMZ single, indicating that SOX9 shRNA and PDK1 inhibitor could significant enhance the suppressing effect of TMZ on nude mice tumor growth." (PMID 29416606, 2018). "Previous studies reported that miR-105 might target several mRNAs, such as mRNAs of SOX9, SUZ, and NCOA1, which are involved in tumor behavior and malignant progression." (PMID 29282124, 2017). "In our study, it was precisely these cell-clusters which completely lacked Sox9 protein expression, while most of the surrounding tumour cells showed a strong antigen reaction." (PMID 29158570, 2017). "Furthermore, the level of SOX9 as well as CSC marker CD44 and mesenchymal marker vimentin in tumor xenografts was dramatically diminished by the treatment." (PMID 29237490, 2017). "Majority of SOX9 positive HCC cases were negative for SOX9 expression in large portions of tumour tissue and SOX9 positive staining’s were found only in single cells." (PMID 29121666, 2017). "It was evident that the amount and the intensity of positive cells in the tumour surrounding brain tissue did not correlate with the extent of Sox9 expression in the respective tumour tissue." (PMID 29158570, 2017). "During the analysis of the aCP samples, it became apparent that not all cells within the tumour bulk revealed nuclear staining for Sox9." (PMID 29158570, 2017).